FAM117A (family with sequence similarity 117 member A)
Tractability: PROTAC: ubiquitination databases record sites on it.
Gene: Protein-coding gene on chromosome 17 (49,710,332 to 49,789,180, reverse strand). Ensembl gene ENSG00000121104.
Subcellular location (Human Protein Atlas): Nucleoplasm
Genetic constraint (gnomAD): Loss-of-function variants: 21 observed, 39.44 expected, observed/expected ratio (o/e) 0.53, 90% interval 0.38 to 0.77. The upper end of that interval is the gene's LOEUF score, 0.77, which puts it in group 3 of 6, group 1 being the genes least tolerant of losing a copy. Missense variants: 447 observed, 540.74 expected, observed/expected ratio (o/e) 0.83, 90% interval 0.76 to 0.89. Synonymous variants: 197 observed, 214.7 expected, observed/expected ratio (o/e) 0.92, 90% interval 0.82 to 1.03.
Homologues: Orthologues: chimpanzee FAM117A (99% identical), macaque SLC35B1 (98% identical), pig FAM117A (94% identical), dog FAM117A (93% identical), rat Fam117a (88% identical), mouse Fam117a (88% identical), guinea pig FAM117A (85% identical), rabbit FAM117A (85% identical), zebrafish fam117aa (34% identical), zebrafish fam117ab (26% identical). Paralogues in human: FAM117B (38% identical), GLCCI1 (37% identical).
Diseases named in the same sentence as FAM117A in open-access papers:
FAM117A is named in the same sentence as 7 diseases in open-access papers, as found by Europe PMC text mining. Sharing a sentence is not in itself a finding about the gene and the disease. The quoted sentences say what the papers report.
lung carcinoma (2 papers, 2019 to 2022). "FAM117A may therefore be associated with progression of lung cancer." (PMID 31407494, 2019). "To further confirm the tumor suppressor roles of FAM117A in lung cancer cells, we next modulated its expression by lentivirus-based overexpression or RNA interference targeting its coding region." (PMID 35280504, 2022). "Consistently, further evidence as demonstrated by the Gene Ontology analysis of the differentially expressed genes, predicted the potential role of FAM117A as a tumor suppressor in lung cancers." (PMID 35280504, 2022). "In the current study, we identified FAM117A as a new regulator for cell cycle control through bioinformatics analysis of transcriptome data of lung cancer patients." (PMID 35280504, 2022). "To determine the potential involvement of FAM117A in lung cancer development, we first analyzed the expression pattern of FAM117A at transcript level in lung cancer tissue and normal tissues using a transcriptome dataset from the TCGA database." (PMID 35280504, 2022). "In summary, our work identified FAM117A as a new prognostic marker for poor outcomes of lung cancer patients, predicting sensitivity to PD0332991 treatment." (PMID 35280504, 2022). "The next set of questions were to identify how FAM117A regulates lung cancer cell growth." (PMID 35280504, 2022). "Collectively, decreased FAM117A expression might be a new biomarker for determining the sensitivity of lung cancer patients to PD0332991." (PMID 35280504, 2022). "Collectively, our findings provide new evidence for FAM117A as an unfavorable prognostic marker for lung cancer patient survival and might be a new biomarker to predict the sensitivity to CDK4/6 inhibitors." (PMID 35280504, 2022). "Considering that the cell cycle from G1 to S phase was dramatically promoted in lung cancer cells with decreased FAM117A expression, we next checked whether this can be restrained by CDK4/6 inhibition." (PMID 35280504, 2022). "Collectively, the expression of FAM117A is significantly decreased in lung cancer tissue." (PMID 35280504, 2022). "In summary, FAM117A might be a negative regulator of lung cancer cell cycle progression." (PMID 35280504, 2022).
gastric cancer (1 paper, 2025). A primary or metastatic malignant neoplasm involving the stomach. "In gastric cancer, the higher expression of FAM117A is associated with a poorer prognosis, although the difference is not statistically significant (p > 0.05)." (PMID 41542087, 2025). "We further investigated the potential target genes or proteins influenced by FAM117A and PIGU in the development of gastric cancer cells." (PMID 41542087, 2025). "Our study has identified the potential regulatory roles of FAM117A and PIGU in gastric cancer development through multi-omics analysis and cellular experiments, but several limitations should be noted." (PMID 41542087, 2025). "Among the previous findings, this study identified FAM117A and PIGU as crucial genes involved in the gastric cancer continuum, suggesting that dysregulation of cell proliferation and alterations in cell adhesion molecule (CAM) expression contribute significantly to gastric cancer development." (PMID 41542087, 2025).
lymph node metastasis (1 paper, 2019). "In this study, we identified 4 coding genes associated with overall survival in LUAD patients with lymph node metastasis, namely, LDHA, ABAT, FAM117A and INPP5J, in the training set." (PMID 31015800, 2019).
non-small cell lung carcinoma (1 paper, 2024). A group of at least three distinct histological types of lung cancer, including non-small cell squamous cell carcinoma, adenocarcinoma, and large cell carcinoma. "A further investigation was undertaken to construct a radiation prediction model for early-stage or locally progressed non-small cell lung cancer (NSCLC) using six genes, including APOBEC3B, GOLM1, FAM117A, KCNQ1OT1, PCDHB2, and USP43." (PMID 38613804, 2024).
cancer (5 papers, 2019 to 2023). A tumor composed of atypical neoplastic, often pleomorphic cells that invade other tissues. "This was confirmed in functional studies demonstrating that FAM117A suppresses cell proliferation in human cancer cell lines." (PMID 37900285, 2023). "Decreased expression of FAM117A in cancerous tissues was also observed in other types of cancers." (PMID 35280504, 2022). "However, ABAT and FAM117A remain inadequately investigated in cancer-related research." (PMID 31015800, 2019). "Limited studies found contradictory roles of FAM117A and FAM117B in cancer." (PMID 37900285, 2023). "We obtained a six-gene signature (APOBEC3B, GOLM1, FAM117A, KCNQ1OT1, PCDHB2, and USP43) with the ability to predict overall survival and progression-free survival (PFS), which could translate into a prediction of the response to the cancer treatment received." (PMID 35565183, 2022).
tumor (2 papers, 2022 to 2025). "The Fam117a gene has been identified as a critical regulator of gene expression, particularly in processes involving cellular proliferation, immune modulation, and tumor suppression." (PMID 39861471, 2025).
FAM117A also shares sentences with these, for which no sentence is quoted: lung adenocarcinoma (1 paper).